ZNF277 (zinc finger protein 277)
Description:
Probable transcription factor. Involved in modulation of cellular senescence; represses transcription of the tumor suppressor gene INK4A/ARF, perhaps acting via the Polycomb group (PcG) complex PRC1.
Synonyms: NRIF4; ZNF277P
Tractability: Antibody: the Human Protein Atlas places it where antibodies can reach. PROTAC: ubiquitination databases record sites on it.
Target class: Transcription factor
Gene: Protein-coding gene on chromosome 7 (112,206,695 to 112,356,519, forward strand). Ensembl gene ENSG00000198839.
Subcellular location: Nucleus
Subcellular location (Human Protein Atlas): Nucleoplasm; Plasma membrane
Gene Ontology:
Molecular function: RNA polymerase II cis-regulatory region sequence-specific DNA binding
Cellular component: nucleus
Genetic constraint (gnomAD): Loss-of-function variants: 41 observed, 46.31 expected, observed/expected ratio (o/e) 0.89, 90% interval 0.69 to 1.15. The upper end of that interval is the gene's LOEUF score, 1.15, which puts it in group 5 of 6, group 1 being the genes least tolerant of losing a copy. Missense variants: 453 observed, 486 expected, observed/expected ratio (o/e) 0.93, 90% interval 0.86 to 1.01. Synonymous variants: 158 observed, 170.1 expected, observed/expected ratio (o/e) 0.93, 90% interval 0.81 to 1.06.
Homologues: Orthologues: chimpanzee ZNF277 (99% identical), macaque ZNF277 (98% identical), dog ZNF277 (91% identical), pig ZNF277 (91% identical), rabbit ZNF277 (88% identical), guinea pig ZNF277 (88% identical), mouse Zfp277 (87% identical), rat Zfp277 (87% identical), tropical clawed frog znf277 (68% identical), zebrafish znf277 (60% identical), Caenorhabditis elegans ztf-7 (39% identical), Drosophila melanogaster CG9890 (34% identical).
Diseases named in the same sentence as ZNF277 in open-access papers:
ZNF277 is named in the same sentence as 16 diseases in open-access papers, as found by Europe PMC text mining. Sharing a sentence is not in itself a finding about the gene and the disease. The quoted sentences say what the papers report.
colon cancer (3 papers, 2014 to 2024). "Next, to pursue our observation that Zfp277 was selectively downregulated in colon tumors from M3R-deficient mice with attenuated tumorigenesis, we examined the role of ZNF277/Zfp277 in colon neoplasia." (PMID 35015732, 2022). "Using human and murine intestine, human colon cancer cells, and ApcMin/+ mice with dysregulated β-catenin signaling and exuberant intestinal neoplasia, we explored the actions of ZNF277/Zfp277 and defined the underlying mechanisms." (PMID 35015732, 2022). "In both human colon cancer cells and the murine colon, ZNF277/Zfp277 deficiency induced p21WAF1 expression and promoted senescence." (PMID 35015732, 2022). "Per cBioPortal, ZNF277 gene mutations causing mostly missense changes were identified in approximately 2.5% of more than 3000 colon cancer specimens." (PMID 35015732, 2022). "Previously, using 12 archived human colon cancer tissues, we detected ZNF277 mRNA overexpression in cancer compared with adjacent normal colon mucosa." (PMID 35015732, 2022). "To gain additional insights into the role of ZNF277 in modulating cellular senescence, we examined the effect of ZNF277 CRISPR KO in colon cancer cells on markers for the senescence-associated secretory phenotype." (PMID 35015732, 2022). "In silico analysis using publicly available online databases — Oncomine, the Gene Expression Profiling Interactive Analysis (GEPIA), and the Human Protein Atlas — revealed increased ZNF277 mRNA and protein levels in colon cancer compared with normal colon." (PMID 35015732, 2022). "IHC staining of murine adenomas, human colon cancer cells, colon cancer cell xenografts, and colon cancers revealed that ZNF277/Zfp277 protein overexpression was localized to cell nuclei." (PMID 35015732, 2022). "We found that ZNF277 inhibits cellular senescence by repressing p21WAF1 expression in human colon cancer cells." (PMID 35015732, 2022). "Zinc finger protein 277 (ZNF277; murine Zfp277), a transcription factor regulating cellular senescence, is overexpressed in colon cancer, but its actions in intestinal homeostasis and neoplasia are unclear." (PMID 35015732, 2022). "The role of zinc finger protein 277 in colon cancer and its relationship to M3R expression and activation are worthy of further investigation." (PMID 24694019, 2014). "Future work will use both in vitro and in vivo approaches to address these questions and elucidate the functional role of ZNF277 and its interaction with M3R in colon cancer." (PMID 24694019, 2014). "The biological importance of this observation is strengthened by finding increased expression of ZNF277 in human colon cancer with a parallel increase in M3R expression." (PMID 24694019, 2014). "Next, we validated the importance of these changes in gene expression by measuring and comparing M3R and ZNF277 protein expression in an archived set of 23 formalin-fixed paraffin-embedded colon cancer tissues with adjacent normal colon from the same patients." (PMID 24694019, 2014). "In these 12 human tissue samples, over-expression of ZNF277 in colon cancer was contingent upon over-expression of CHRM3 (Spearman rank correlation coefficient = 0.73)." (PMID 24694019, 2014). "Collectively, these data support the novel conclusion that in both murine and human colon cancer, zinc finger protein 277 plays a currently undefined role in M3R-mediated promotion of neoplasia." (PMID 24694019, 2014). "Our in silico analysis of this existing dataset revealed that ZNF277 expression was significantly up-regulated in 33 of 34 colon cancers compared to adjacent normal colon (P = 2 × 10-8)." (PMID 24694019, 2014). "Confidence in this conclusion was bolstered by detecting over-expression of both mRNA and protein for ZNF277, the human analogue of Zfp277, in human colon cancer samples and, importantly, that this over-expression mirrored that of CHRM3 and M3R." (PMID 24694019, 2014).
colon cancer (continued). "Indeed, our studies in a murine model of genetic colon cancer, ApcMin/+ mice, supports an important role for ZNF277/Zfp277 in intestinal neoplasia." (PMID 35015732, 2022). "To identify the binding site(s) for β-catenin/TCF/LEF in the ZNF277 promoter in HT29 human colon cancer cells with robust β-catenin and ZNF277 expression, we performed ChIP assays using quantitative PCR (qPCR) primers for each potential site with ChIP-grade anti–β-catenin antibodies." (PMID 35015732, 2022). "To determine whether ZNF277 deficiency affects cell proliferation in vivo, we examined the effect of CRISPR KO of ZNF277 on the growth of human colon cancer cell xenografts." (PMID 35015732, 2022). "Here, we showed that ZNF277 also interacts with BMI1 in human colon cancer cells, although the functional significance of this interaction and whether ZNF277 is a component of the PRC1 complex in intestinal epithelial cells remains to be determined." (PMID 35015732, 2022). "Additionally, we used human colon cancer cells, and animal and enteroid models, to elucidate the mechanisms whereby ZNF277/Zfp277 overexpression promotes colon neoplasia." (PMID 35015732, 2022). "To determine whether ZNF277 interacts physically with BMI1 in humans, we performed co-IP using protein extracts from SNUC4 human colon cancer cells; these experiments showed robust ZNF277 and BMI1 protein expression." (PMID 35015732, 2022). "Hence, a novel, hitherto unrecognized role for ZNF277 in colon cancer biology is certainly plausible." (PMID 24694019, 2014). "Notably, mRNA and protein for ZNF277, the human analogue of Zfp277, were increased in human colon cancer compared to adjacent normal colon, along with parallel changes in expression of M3R." (PMID 24694019, 2014). "Although finding an association between ZNF277 and M3R over-expression in human colon cancer is reassuring, we do not currently understand the molecular mechanism underlying this interaction." (PMID 24694019, 2014). "Likewise, in an archived set of 23 formalin-fixed paraffin-embedded human colon cancer tissues, we used IHC to detect ZNF277 protein overexpression in tumors compared with adjacent normal colon from the same person; ZNF277 was primarily localized to tumor cell nuclei." (PMID 35015732, 2022). "In 3 human colon cancer cell lines, siRNA knockdown of β-catenin (CTNNB1) dose-dependently reduced ZNF277 protein expression." (PMID 35015732, 2022). "Overall, our findings uncover ZNF277/Zfp277 as a potentially novel intestinal transit-amplifying cell (TAC) marker and colon cancer oncogene." (PMID 35015732, 2022). "In human HT29 and H508 colon cancer cells and HEK293 cells with siRNA- or CRISPR-induced reduction of ZNF277 expression, we detected strikingly increased p21WAF1 levels." (PMID 35015732, 2022). "Our findings identify ZNF277/Zfp277 as both a TAC marker and colon cancer oncogene that regulates cellular proliferation and senescence, in part by repressing p21WAF1 expression." (PMID 35015732, 2022).
autism (2 papers, 2010 to 2014). Persistent deficits in social interaction and communication and interaction as well as a markedly restricted repertoire of activity and interest as well as repetitive patterns of behavior. "Given prior observations of phenotypic and genetic overlaps between SLI and autism, as well as the genomic position of the ZNF277 gene within a known ASD risk locus, we postulated that the disruption of this gene may be relevant for both disorders." (PMID 24518835, 2014). "Human ZNF277 was first documented as a gene located on chromosome 7 at q31 that is often deleted in several malignancies and autism." (PMID 20808772, 2010). "However, screening of a cohort of ASD multiplex families found that the frequency of ZNF277 microdeletions in individuals with autism was similar to that observed in controls." (PMID 24518835, 2014).
chronic lymphocytic leukemia (1 paper, 2014). "ZNF277 over-expression is reported in other cancers – chronic lymphocytic leukemia, well-differentiated renal cell carcinoma, and germ cell and endocrine tumors." (PMID 24694019, 2014).
colon adenocarcinoma (1 paper, 2022). "Analyzing data extracted from the Colon Adenocarcinoma (COAD) data set (GEPIA), we did not detect a relationship between ZNF277 levels and CRC survival." (PMID 35015732, 2022).
diabetes (1 paper, 2014). "Ontological classification demonstrates that these 14 genes are associated with diabetes (ALMS1P; RAET1L; GYS1; RBM47; EFR3B), cancer (RPL27A; SPAM1; PTCH1; ZNF277; USP35; CDC86), or metabolism (C3orf15; AOC2; GOT1)." (PMID 24885560, 2014).
lymph node metastasis (1 paper, 2022). "In the present study, analysis of ZNF277 expression using 4 online cancer databases revealed that both ZNF277 transcript and protein levels were increased in CRC specimens from men and women of all ages and races, with a variety of cancer stages and lymph node metastasis." (PMID 35015732, 2022).
osteoporosis (1 paper, 2024). A condition of reduced bone mass, with decreased cortical thickness and a decrease in the number and size of the trabeculae of cancellous bone (but normal chemical composition), resulting in increased fracture incidence. "In addition, cluster 2 contained transcripts without prior established association with BMD, osteoporosis or bone cell signaling (e.g., IL31RA, ELTD1, ZNF277)." (PMID 38791593, 2024).
cancer (6 papers, 2014 to 2025). A tumor composed of atypical neoplastic, often pleomorphic cells that invade other tissues. "According to the analysis of available human tumours from the Human Protein Atlas project, overexpression of ZNF277 is associated with improved prognosis in human cancers." (PMID 39964832, 2025). "In contrast, overexpression of PRMT3 reduces the amount of the ZNF277–uS5 complex, which is linked to poor prognosis in human cancers." (PMID 39964832, 2025). "The leading pathways impacted by ZNF277 deficiency included increased p21WAF1 expression in cancer stem cell signaling, proteoglycans in cancer, and PI3K/AKT signaling." (PMID 35015732, 2022). "To identify human ZNF277 target genes in cancer cells, we performed RNA-Seq using RNA isolated form HT29 cells with and without ZNF277 CRISPR KO (n = 3 for both)." (PMID 35015732, 2022). "The protein product, zinc finger protein 277, is reported to play a role in cellular senescence and protection against genomic instability and cancer." (PMID 24694019, 2014). "Zinc finger protein 277 and M3R were both significantly over-expressed in cancer compared to adjacent normal tissue." (PMID 24694019, 2014). "Lastly, inhibiting ZNF277 may increase p21WAF1 expression and promote cell cycle arrest in cancer cells." (PMID 35015732, 2022). "The opposing effects of ZNF277 and PRMT3 expression on human cancer prognosis suggest that targeting the ribosomal uS5 may reduce the growth of human cancers." (PMID 39964832, 2025).
tumor (3 papers, 2014 to 2022). "Reduced tumor formation was associated with strikingly prolonged survival in both male and female mice, suggesting that ZNF277 may be an important CRC oncogene." (PMID 35015732, 2022). "In doing so, we identified ZNF277 as a transcriptional target of β-catenin signaling that modulates Wnt/β-catenin and polycomb protein signaling, and it represses p21WAF1 expression, thereby regulating intestinal epithelial cell proliferation, senescence, and neoplasia." (PMID 35015732, 2022). "In silico analysis using the UALCAN server revealed that, regardless of sex, race, age, tumor stage, and nodal metastasis, ZNF277 transcript levels are 1.5- to 2.0-fold greater in tumors compared with normal tissues." (PMID 35015732, 2022). "Because ZNF277 is expressed in many tissues, including the immune system, ZNF277 expression levels in tumor cells alone might not be sufficient to alter survival." (PMID 35015732, 2022). "Some of these genes may be involved in the proliferation and invasion of tumor cells; for example, NYAP2 is reported to activate PI3K, Akt and Rac1, and mediates remodeling of the actin cytoskeleton, whereas ZNF277 regulates cell migration and invasion through phosphatase and tensin homolog (PTEN)." (PMID 32986753, 2020).
infection (1 paper, 2025). The state of being infected such as from the introduction of a foreign agent such as serum, vaccine, antigenic substance or organism. "To confirm this, we examined the expression level of circ-ZNF277 in the THP-1 cells infected with Mtb at different multiplicities of infection (MOI) via quantitative real-time PCR (qPCR)." (PMID 39996735, 2025). "At the MOIs of 5 and 10, the intracellular levels of circ-ZNF277 increased by two-fold and three-fold, respectively, at 12 h post-infection." (PMID 39996735, 2025). "The CFU counting showed that the survival rate of Mtb in the circ-ZNF277-suppressed THP-1 cells was significantly increased compared with the controls at 12 and 24 h post-infection (p < 0.05)." (PMID 39996735, 2025). "The qPCR experiment showed that the transcription levels of IL-1β, IL-6, and TNF-α in the circ-ZNF277 suppressed THP-1 cells were lower than those in the control THP-1 cells at 0, 12, and 24 h post-infection (p < 0.001)." (PMID 39996735, 2025).
ZNF277 also shares sentences with these, for which no sentence is quoted: adenoma (1 paper); autistic spectrum disorders (1); colorectal cancer (1); Esophageal Carcinoma (1); renal cell carcinoma (1); specific language impairment (1).